CYP2C19 (cytochrome P450 family 2 subfamily C member 19)
Diseases named in the same sentence as CYP2C19 in open-access papers (continued):
Sharing a sentence is not in itself a finding about the gene and the disease.
myocardial infarction (42 papers, 2010 to 2026). Gross necrosis of the myocardium, as a result of interruption of the blood supply to the area, as in coronary thrombosis. "One influential achievement in myocardial infarction pharmacogenomics is the association between CYP2C19 gene polymorphism and cardiovascular disease." (PMID 39960900, 2025). "Pharmacogenomic testing for CYP2C19 helps personalise clopidogrel therapy and reduces the risk of experiencing a secondary myocardial infarction in individuals with impaired CYP2C19 function." (PMID 40280918, 2025). "The objective of this study was to assess prevalence of common CYP2C19 genotype polymorphisms in a British–South Asian population and correlate these with recurrent myocardial infarction risk in participants prescribed clopidogrel." (PMID 37808344, 2023). "Multivariable logistic regression was used to test for association between genetically inferred CYP2C19 metabolizer status and recurrent myocardial infarction, controlling for known cardiovascular disease risk factors, percutaneous coronary intervention, age, sex, and population stratification." (PMID 37808344, 2023). "In addition, CYP2C19 inhibition in a clinical study involving readmitted patients with myocardial infarction, demonstrated an increased risk of reinfarction." (PMID 35811736, 2022). "Over a follow-up of 12 months, the incidence of recurrent angina, acute myocardial infarction, and intra-stent thrombosis in CYP2C19 681 GG carriers was significantly lower than that in CYP2C19 681A allele (GA + AA) group (2/59 vs. 8/51, 1/59 vs. 6/51, 0 vs. 4/51, respectively, p < 0.05)." (PMID 26147597, 2015). "In fact, we have encountered patients who experienced two consecutive myocardial infarctions despite clopidogrel therapy, later attributed to reduced bioactivation confirmed by CYP2C19 genotyping." (PMID 40559107, 2025). "The objectives of this study were to assess CYP2C19 genotypes in a British–South Asian ancestry cohort and to correlate inferred metabolizer phenotypes with recurrent myocardial infarction (MI) events in participants prescribed clopidogrel." (PMID 37808344, 2023). "In the acute myocardial infarction (AMI) subgroup, we observed a significant association of CYP2C19 phenotypes and 1-year MACCE-free survival (NM + RM: 94.6% vs. IM: 91.2% vs. PM: 77.5%, p = 0.007)." (PMID 36072879, 2022). "In conclusion, in elderly patients who maintained standard DAPT after PCI, poor metabolizers of CYP2C19 had poor clinical outcomes regarding death and myocardial infarction." (PMID 33707344, 2021). "The incidence of endpoints (including ischemic stroke, hemorrhagic stroke, and myocardial infarction) in patients taking clopidogrel under the guidance of the CYP2C19 was low." (PMID 33685396, 2021). "For CYP2C19, the primary endpoint, defined as the composite of myocardial infarction and death, was significantly higher in the poor metabolizer group than in the other group (PM vs NM or IM; 8.7% vs. 4.4%)." (PMID 33707344, 2021). "For example, clopigodrel, a commonly prescribed antiplatelet medication following myocardial infarction, is a prodrug primarily metabolized by CYP2C19 (among other CYPP450 enzymes) into its active metabolite." (PMID 34615849, 2021). "Participants felt strongly that pre-emptive PGx testing via the GP was preferable to point of care testing in hospital at the time of indication for therapeutic (ie in the example of CYP2C19 testing to help guide anti-platelet choice after a myocardial infarction)." (PMID 37907686, 2023). "The incidence of the primary endpoint events (including ischemic stroke, hemorrhagic stroke, and myocardial infarction cases) of CYP2C19 genotype-guided group decreased compared to the non-genotype-guided group, and so did the recurrence rate of ischemic stroke." (PMID 33685396, 2021).
coronary artery disease (41 papers, 2013 to 2025). "Meanwhile, the prevalence of CYP2C19*2 and CYP2C19*3 is as high as 36.6% in Chinese patients with coronary heart disease, and studies on these polymorphisms associated with bleeding events among patients with ACS in China are limited." (PMID 36829258, 2023). "This study aimed to investigate the association between CYP2C19 polymorphisms and clopidogrel resistance (CR) in patients with coronary heart disease and ischemic stroke among Han and Tibetan populations in Qinghai Province, China." (PMID 36325266, 2022). "In this study, we investigated the association between ∗2, ∗3, and ∗17 allelic variants of the CYP2C19 gene and CR in patients with coronary heart disease and ischemic stroke among Han and Tibetan populations." (PMID 36325266, 2022). "In this study, we intended to investigate the association of CYP2C19 polymorphisms with CR in patients with coronary heart disease and ischemic stroke among Han and Tibetan populations in Qinghai Province, China." (PMID 36325266, 2022). "This study will provide a better understanding of the association between CYP2C19 polymorphisms and coronary heart disease risk." (PMID 33327349, 2020). "The loss of function CYP2C19*2 genotypes are associated with poor metabolism of clopidogrel, as well as with a higher rate of adverse cardiovascular events in coronary heart disease patients." (PMID 29707143, 2018). "In patients with coronary artery disease carrying the genetic variant associated with a loss of function of the CYP2C19 enzyme, the risk for stent thrombosis is 3–6 times higher with clopidogrel treatment." (PMID 26147597, 2015). "We investigated the prognostic value of carriage of the CYP2C19*2 allele in a high risk group of patients with prevalent coronary heart disease (CHD) at baseline during long-term follow-up under conditions of routine clinical care." (PMID 23981380, 2013). "CyPallGlo was used to identify CYP2C19 polymorphisms in 363 patients with coronary heart disease." (PMID 38286794, 2024). "The case-control study analyzed the relationship between CYP2C19 polymorphism and the development of coronary artery disease (CAD) when dyslipidemia, diabetes, and chronic kidney disease are not present to reduce the impact of conventional coronary risk determinants." (PMID 38021526, 2023). "In addition, polymorphisms in the CYP2C19 gene have been reported to be positively associated with cardiovascular diseases, such as coronary artery disease and atherosclerosis." (PMID 35814206, 2022). "Furthermore, genetic polymorphism of CYP2C19 was shown to be an independent predictor of clopidogrel resistance in Korean subjects with coronary artery disease." (PMID 24723825, 2014). "Recent studies in patients with coronary artery disease investigated pharmacogenomics based on CYP2C19 gene variations to optimize therapy." (PMID 36627677, 2023). "This study aimed to investigate the relationship between sdLDL-C and coronary artery disease (CAD) risk factors and explore the influence of CYP2C19 metabolizer phenotypes on the sdLDL-C lowering efficacy of statins." (PMID 36601065, 2022). "In this study, 213 Chinese patients with coronary heart disease were included and the influence of ABCC2 gene polymorphisms (rs717620, rs2273697, and rs3740066), CYP2C19*2, and CYP2C19*3 on clopidogrel response were analyzed." (PMID 36278153, 2022). "This conclusion is consistent with that of a previous study, and in addition to CYP2C19, N6AMT1 rs2254638 polymorphism also had an effect on clopidogrel resistance in Chinese patients with coronary heart disease." (PMID 36278153, 2022). "In patients with stable coronary heart disease, CYP2C19*2 heterozygous carriers taking 225 mg of clopidogrel per day were shown to achieve the same antiplatelet effect with CYP2C19 wild-type patients taking 75 mg of clopidogrel per day." (PMID 33915807, 2021).
coronary artery disease (continued). "It has been shown that genetic polymorphisms resulting in reduced function of cytochrome P450 2C19 (CYP2C19) were associated with increased cardiovascular risk and mortality in coronary artery disease patients on clopidogrel treatment." (PMID 32013012, 2020). "In the field of coronary heart disease, CYP2C19 genotyping has been determined to become straightforwardly diagnostic approach for optimal clopidogrel treatment." (PMID 29901608, 2018). "ADP induced platelet aggregation level by CYP2C19*2, *3 and PON1 Q192R polymorphisms in clopidogrel treated patients with coronary artery disease." (PMID 25329996, 2014). "This is perhaps not surprising as the participants all have coronary artery disease already by definition but highlights the utility of CYP2C19 genotyping as compared with clinical risk stratification." (PMID 37808344, 2023). "However, there are limited data in East Asia that have focused on CYP2C19 genotype-guided antiplatelet therapy in patients with coronary heart disease." (PMID 33551797, 2020). "Polymorphisms in the cytochrome P450 2C19 (CYP2C19) gene have been reported to be associated with coronary heart disease (CHD), but the results were not consistently analyzed among different patient groups." (PMID 33327349, 2020). "However, in our previous study, the frequency of CYP2C19*3 was noted to be 6.250% in coronary artery disease (CAD) patients in a Chinese population." (PMID 23555019, 2013). "Similarly, it was reported in a study using stable coronary artery disease patients that approximately 18–25% of the CYP2C19 *1/ *1 carriers and 38–43% of the CYP2C19 *1/ *2 carriers demonstrated high platelet reactivity following clopidogrel administration." (PMID 23431496, 2013). "The relationship between Cytochrome P450 2C19 (CYP2C19) polymorphisms and coronary artery disease (CAD) in hypertensive patients was analyzed." (PMID 40715000, 2025). "A total of 200 patients undergoing PCI in our hospital due to complex coronary artery disease from February 2019 to February 2021 were selected and divided into the control group and the observation group according to whether CYP2C19 gene detection was performed." (PMID 35223980, 2022). "A non-randomized prospective study of 168 patients with coronary artery disease investigated the correlation between CYP2C19 and ABCB1 and ischemic events." (PMID 35806936, 2022). "Furthermore, an observational study in Chinese patients with coronary artery disease indicated that CYP2C19 genotype-based antiplatelet therapy did not improve clinical outcomes." (PMID 40421189, 2025).
ischemic stroke (38 papers, 2012 to 2026). A stroke disorder caused by obstruction of blood flow to the brain, due to thrombotic (local blood clot formation) or embolic (due to a blood clot or other material traveling from another site) event. "This study investigated the relationship between CYP2C19 polymorphisms and the expression of selected platelet microRNAs in patients with ischemic stroke treated with clopidogrel." (PMID 40886375, 2025). "Loss-of-function variants in CYP2C19 influence an individual's ability to metabolize clopidogrel, increasing the risk of secondary vascular events following ischemic stroke and percutaneous coronary intervention." (PMID 39725012, 2025). "The present study demonstrated that some CYP2C19 single-nucleotide polymorphisms affect platelet aggregation inhibition differently for prasugrel and clopidogrel in patients with ischemic stroke." (PMID 40229530, 2025). "A study has found that CYP2C19*2 and CYP2C19*3 allele variants significantly increase the probability of ischemic stroke recurrence." (PMID 39472784, 2024). "CYP2C19 loss-of-function was associated with increased risk of ischemic stroke after transient ischemic attack." (PMID 39472784, 2024). "CYP2C19 loss-of-function was associated with increased risk of first-time ischemic stroke for intracranial atherosclerotic disease patients treated with clopidogrel after transient ischemic attack." (PMID 37024851, 2023). "The current study also found CYP2C19 as a candidate gene that increased the risk of vascular events in ischemic stroke patients." (PMID 37342754, 2023). "Within 24 h of the symptoms onset, eligible patients (minor ischemic stroke or high-risk TIA) only carrying CYP2C19 loss-of-function alleles were included in the CHANCE-2 trial." (PMID 36744212, 2022). "In this study of 7483 UK Biobank primary care patients prescribed clopidogrel, carriers of CYP2C19 LoF alleles had substantially increased risks of incident ischaemic strokes and MI." (PMID 34903548, 2021). "Polymerase chain reaction-restriction fragment length polymorphism was used to examine CYP2C19*2 (681G>A) and CYP2C19*3 (636 G>A) genotype distributions in ischemic stroke patients." (PMID 28064328, 2017). "ADP induced platelet aggregation level by CYP2C19 polymorphisms in clopidogrel treated patients with ischemic stroke." (PMID 28064328, 2017). "The aim of our study was, therefore, to assess the influence of CYP2C19 genetic polymorphisms on the response to clopidogrel in ischemic stroke in Saudi Arabian population." (PMID 28064328, 2017). "The occurrence of composite outcome (recurrence of transient ischemic attack/ischemic stroke or death) was evaluated for association with genetic variants of CYP2C19 (allele *2, *17, *3, and *4, i.e., single nucleotide polymorphism (SNP) 1/2/3/4, identified using TaqMan assays and DNA sequencing)." (PMID 37342754, 2023). "Intermediate and poor CYP2C19 metabolizers had a higher risk of ischemic stroke recurrence." (PMID 37024851, 2023). "For larger artery atherosclerotic stroke patients in subacute phase within 7 days after onset, PRAISE study, a multicenter study in Japan, showed that a higher PRU (>254) was more strongly associated with early recurrence of ischemic stroke than CYP2C19 PM genotype." (PMID 36090856, 2022). "In conclusion, we discovered CYP2C19 polymorphisms were associated with the clinical outcome of elderly ischemic stroke patients by comparing whether they took clopidogrel under the guidance of CYP2C19." (PMID 33685396, 2021). "In lifetable estimates based on observed incidence rates from 36 to 79 (the minimum and maximum ages at which clopidogrel was first prescribed) the risk of ischaemic stroke in CYP2C19 LoF carriers was 22.5% (95% CI 14.4% to 34.0%), compared with 15.4% (95% CI 11.4% to 20.5%) in non-carriers." (PMID 34903548, 2021).
ischemic stroke (continued). "In patients with ischaemic stroke who had a single CYP2C19 loss-of-function allele and moderate to severe cerebral stenosis, fewer vascular events occurred within 3 months with high dose of clopidogrel and aspirin than with normal dose of clopidogrel and aspirin." (PMID 33121452, 2020). "Furthermore, reduction of clopidogrel-induced IPA due to CYP2C19 polymorphisms has been reported in patients with ischemic stroke." (PMID 31643039, 2020). "Overall, our findings provide moderate evidence that carriers of CYP2C19 LOF alleles derive less benefit from clopidogrel treatment after ischemic stroke or TIA, suggesting that CYP2C19 genetic testing may be considered to personalize antiplatelet therapy in non-East Asian patients." (PMID 38038819, 2024). "In fact, apart from CYP2C19 polymorphisms, many other genetic polymorphisms that are relevant to the disposition and efficacy of clopidogrel may influence the pharmacodynamic effects of clopidogrel for patients with an ischemic stroke or a TIA." (PMID 33795788, 2021). "Differential effects of CYP2C19 genetic polymorphisms on CYP2C19 inhibitor metabolism have been reported in several PCI studies, but similar reports in ischemic stroke patients are limited." (PMID 40229530, 2025). "These include the accessibility of effective secondary prevention, CYP2C19 genetic makeup, consistent rehabilitation practices, familial backing, the gravity of ischemic stroke, and the kind of acute phase therapy employed." (PMID 39669108, 2024). "In patients with ischaemic stroke who had only one CYP2C19 LoFA and moderate to severe cerebral stenosis, fewer vascular events occurred within 3 months with high dose clopidogrel combined with aspirin than with normal dose clopidogrel combined with aspirin." (PMID 33121452, 2020). "From November 2012 to June 2014, 959 ischemic stroke patients underwent CYP2C19 genotype screening at our hospital." (PMID 27137706, 2016). "Carriers of CYP2C19 loss-of-function alleles who receive clopidogrel are at higher risk of thrombotic events, including recurrent ischemic stroke, than non-carriers." (PMID 40229530, 2025). "In this study, our objective was to evaluate the expression of selected platelet miRNAs (miR-126-3p, miR-19a-3p, miR-19b-3p, miR-22-3p, miR-185-5p) in patients with ischemic stroke who receive clopidogrel according to their genotypic status of CYP2C19 (*1/*1, *1/*2, *2/*2)." (PMID 40886375, 2025). "Carriers of CYP2C19 loss-of-function variants have a 1.6 times greater risk of ischemic stroke than non-carriers." (PMID 39472784, 2024). "CYP2C19 LoF (*2-*8, intermediate/poor metabolisers) carriers (n=2144, 28.7%) were more likely to have an ischaemic stroke while on treatment for clopidogrel than patients without CYP2C19 LoF genetic variants (HR 1.53, 95% CI 1.04 to 2.26, p=0.031)." (PMID 34903548, 2021). "We, therefore, estimate the PAF for ischaemic stroke—the proportion of ischaemic strokes in this population that would not have occurred if clopidogrel efficacy was not affected by CYP2C19 LoF variants—to be 12.9% (95% CI 1.4% to 20.8%)." (PMID 34903548, 2021). "CYP2C19 LoF carriers were not at significantly increased risk of ischaemic strokes compared with non-carriers (HR 1.12, 95% CI 0.93 to 1.35, p=0.24)." (PMID 34903548, 2021). "Our study showed a significant difference with the genotype and allele frequencies of CYP2C19*2 and *3 variants between responders and non-responders groups of clopidogrel in ischemic stroke patients." (PMID 28064328, 2017). "CYP2C19 genotype screening was performed on 959 ischemic stroke patients." (PMID 27137706, 2016). "However, the association between CYP2C19 polymorphisms and platelet miRNA expression has not been adequately explored in the context of ischemic stroke." (PMID 40886375, 2025).
ischemic stroke (continued). "To test whether the effect of CYP2C19 LoF genotypes on ischaemic stroke risk was specific to clopidogrel, and not via a separate but unknown biological mechanism, we analysed the 198 868 UK Biobank participants with general practitioner (GP) prescribing data in whom clopidogrel was never prescribed." (PMID 34903548, 2021). "CYP2C19*2 (G681A and rs4244285), CYP2C19*3 (G363A and rs4986893), CYP2C19*17 (C806T and rs12248560), and ABCB1 (C3435T and rs1045642) carriers with ischemic stroke are particularly sensitive to clopidogrel ADRs." (PMID 32357528, 2020). "CYP2C19*2 carriers and patients with HTPR in the acute phase after ischemic stroke or transient ischemic attacks exhibit higher PRU values, but not long-term treatment HTPR." (PMID 33370281, 2020). "In the present study, ticagrelor/aspirin therapy tended to have stronger platelet inhibition and more rapid onset in platelet inhibition compared with clopidogrel/aspirin therapy irrespective of CYP2C19 metabolizer status in patients with ischemic stroke and TIA." (PMID 33411687, 2020). "In such populations, if aspirin is contraindicated, clopidogrel dose escalation or antiplatelet agents not influenced by CYP2C19 genetic variants, such as ticagrelor and ticlopidine, could be alternative P2Y12 inhibitors for CYP2C19 LOF alleles carriers after ischemic stroke or TIA." (PMID 38038819, 2024).